NF1 (neurofibromin 1)
Diseases named in the same sentence as NF1 in open-access papers (continued):
Sharing a sentence is not in itself a finding about the gene and the disease.
tumor (continued). "Genomic testing revealed increased tumor mutational burden and alterations in NF1, BRAF, CDKN2A/B, TERT." (PMID 34926265, 2021). "We identified and analyzed 12 case reports of appendiceal tumor associated with NF1 reported through an extensive search using PubMed." (PMID 34581917, 2021). "The frequency of mutations and copy number variation loss events of NF1 in different tumour entities is variable." (PMID 35008787, 2021). "Genetic deficiency of NF1 attracts macrophages/microglia into tumors and a macrophage/microglia-rich microenvironment also induces a mesenchymal tumor cell phenotype." (PMID 33618763, 2021). "The important role of NF1 to regulate FOSL1 expression explains the proneural to mesenchymal transition in tumours that acquire NF1 mutations such as MES GBM." (PMID 35008787, 2021). "Cells engineered in this manner would be poised to be used for novel drug discovery for not only NF1-associated malignancies, but many other cancers harboring loss of tumor suppressors or with known oncogenic drivers." (PMID 32353955, 2020). "The wide variation of the clinical expression, the tumor risk and the totally unpredictable evolution of the disease impose regular monitoring of NF1 patients." (PMID 32913647, 2020). "Other NF1-associated tumours are the optic pathway gliomas (OPGs), occurring in approximately 15% of NF1 individuals." (PMID 33066259, 2020). "The three cases (Mice 2, 3, and 6) that maintained tumor precursor cells with normal Pten/chr19 and near-2N genomes all exhibited homozygous Nf1 loss in early phases of tumor evolution." (PMID 32699356, 2020). "Of note, one of our NF1 patients presented a DMG H3 K27M-mutant and currently represents the first description in the literature where this type of tumor is reported in association with a genetically confirmed diagnosis of NF1." (PMID 32582540, 2020). "It appears that at least in NF1-associated MPNSTs, progression from benign to malignant status frequently proceeds through sequential inactivation of three tumor suppressors: NF1, CDKN2A/B, and SUZ12 and/or EED (PRC2 complex)." (PMID 32642732, 2020). "Several studies have demonstrated that the NF1 gene, a tumor suppressor gene, is commonly mutated in GBM." (PMID 33237934, 2020). "NF1 is a tumor suppressor through inhibition of RAS activity, whose mutation is frequently found in BC patients." (PMID 31867841, 2020). "NF1 mutations are involved in chemotherapy and targeted therapy resistance in tumor cells through multiple mechanisms." (PMID 33061844, 2020). "NF1 gene encodes a cytosolic protein of 2818 amino acids, called neurofibromin, which acts as a tumour suppressor molecule." (PMID 33066259, 2020). "It would, therefore, be misleading to use only molecular criteria to define MC-AAP within or outside the setting of background NF1-associated tumor predisposition." (PMID 31677015, 2020). "For other ancestries, the tumor from one predisposing variant carrier of the Native/Latin American ancestry, NF1 p.Y489C, showed low NF1 mRNA expression (2% in BRCA, RNA VAF = 0)." (PMID 32471518, 2020). "Mutated tumor-suppressor genes, such as phosphatidylinositol-4,5-bisphosphate 3-kinase catalytic subunit alpha (Pi3kca), Neurofibromin 1 (Nf1), and Lrig1 were observed." (PMID 32059662, 2020).
tumor (continued). "Future studies into the molecular characterization of orbitofacial NF, and the relevance of HOX genes, will certainly include these variables, given their relevance to the study of NF1-associated neoplasia." (PMID 32366326, 2020). "Given the limited representation of different NF1 tumor types in our genomic variant dataset, we used alternate gene expression metrics to assess the biological underpinnings of the 73 uncharacterized latent variables." (PMID 32098059, 2020). "Among the numerous NF1 mutations reported to date, very few of them correlate with the NF1 tumor phenotype." (PMID 32533764, 2020). "In a next step, we wanted to exclude a loss of function of the tumor suppressor proteins neurofibromin 1 and neurofibromin 2, therefore immunostainings against the respective proteins were applied to all tumor sections." (PMID 32552868, 2020). "We found only one description of a pediatric patient with an HGG and diagnostic criteria of NF1, where evidence of tumor dissemination was reported." (PMID 32582540, 2020). "It is caused by mutations in the NF1 gene, a classic tumor suppressor gene on chromosome 17 (17q11.2) which encodes neurofibromin that is largely expressed in the nervous system." (PMID 32431664, 2020). "Recent advances in our understanding of tumour molecular and cellular pathogenesis will provide opportunities to develop effective treatments in the future for NF1-associated neoplasms." (PMID 32439933, 2020). "NF1 is caused by inactivating mutations of the NF1 tumor-suppressor gene (17q11.2), encoding neurofibromin 1, a negative regulator of the RAS transduction pathway, which regulates basic functions, such as proliferation, differentiation and apoptosis." (PMID 32326947, 2020). "One possible reason for this difference is that fewer discrete signaling dependencies exist with NF1 tumor suppressor loss than cancers that are critically dependent on RAS signaling as a result of activating RAS or EGFR mutations." (PMID 32245042, 2020). "Mesenchymal GBM presents most prominently with deletion or mutations of the tumor suppressor gene, neurofibromin 1 (NF-1)." (PMID 30654536, 2019). "Surprisingly, of all the potential RASGAPs, we identified that only the loss of NF1 resulted in increased tumor growth and EGF-independent cell survival." (PMID 30858928, 2019). "Together, using patient-derived CRC organoids, we reveal that of all RASGAPs with functional GAP domains, only NF1 deficiency promote cell survival and enhanced tumor growth upon challenging EGF signaling conditions in human CRC samples." (PMID 30858928, 2019). "Lastly, the work suggests that tumor stratification by co‐mutations to KRAS/NF1 highlights the LAUD patient population expected to benefit from inhibiting PSAT1." (PMID 31036704, 2019). "The tumor from our 2nd patient had epithelioid/gemistocytic morphology and two different truncating mutations in the NF1 tumor suppressor with LOH." (PMID 31258848, 2019). "Identifying the genetic drivers and the precise sequence of genetic hits in NF1-associated tumor development is still being fully elucidated." (PMID 31462295, 2019). "The 2nd patient’s tumor showed two NF1 somatic mutations predicted to truncate the protein, most likely located on different alleles, indicating loss of heterozygosity (LOH)." (PMID 31258848, 2019). "In relation to mutational co-occurrence, it is conceivable that loss of NF1 can enhance otherwise weak activating mutations of the MAPK signaling pathway to reach optimal levels of pathway activation for efficient tumor growth." (PMID 30858928, 2019). "NF1 encodes neurofibromin, a protein with tumor suppressor function belonging to the family of GTPase activating proteins (GAPs)." (PMID 31487937, 2019).
tumor (continued). "To our knowledge we are the first to present direct loss-of-function data that of all RASGAPs only the loss of NF1 promotes enhanced tumor growth and EGF-independent survival in CRC." (PMID 30858928, 2019). "With this system, tumours that histologically resemble human GBMs were generated, and deep-sequencing revealed co-occurring mutations such as B2m-Nf1 and Mll3-Nf1 as putative driver combinations." (PMID 31505839, 2019). "We also detected the 9p21.3 loss of heterozygosity (LOH) in different tumor types of NF1 patients, supporting the involvement of ANRIL in some NF1-associated tumors." (PMID 31694342, 2019). "NF1 plays a significant role in cancer, as germline loss and homozygous inactivation lead to tumor formation in individuals with NF1." (PMID 31466283, 2019). "The NF1 gene showed 10 somatic mutations in 8 tumor samples (8.8%), three of which were already known mutations (2 missense and 1 nonsense mutations), four were novel missense mutations, and three were novel frameshift mutations." (PMID 31548566, 2019). "Our previous study showed that the non-steroidal analog of 2ME2, STX3451, caused microtubule depolymerization and cell death in NF1 deficient tumour cells, even in the presence of elevated hormones." (PMID 31730023, 2019). "Along this line, several genetic models with mutations in the orthologs of the human NF1 gene have been created and shown to recapitulate many aspects of the disease, including tumor formation and cognitive and behavioral impairments." (PMID 31600280, 2019). "The 8454-nucleotide open reading frame of the NF1 gene (NM_00267.3) encodes a 2818-amino-acid protein, neurofibromin, which shows tumor suppressor function by negatively regulating the RAS-MAPK pathway." (PMID 31443423, 2019). "To identify the genes that are directly regulated by Runx, we performed chromatin immunoprecipitation sequencing (ChIP-seq) to assess the genome-wide occupancy of RUNX1 in Nf1-deficient tumor cells." (PMID 31032403, 2019). "The neoplasms with NF1 pathogenic mutations harbored a range of morphologies, from predominantly spindle cell in 5 cases, to giant cell, gemistocytic or epithelioid in one case, each." (PMID 31258848, 2019). "Whereas reports on the frequency of genetic alterations of NF1 in CRC show varying results, a recent study associated mutant NF1 with tumor progression and anti-EGFR therapy resistance." (PMID 30858928, 2019). "Our previous studies on NF1 cell lines demonstrated that STX3451 caused nuclear fragmentation in both the NF1-null malignant tumour cell line ST88 and in benign plexiform neurofibroma (PNF) cells, although this result was less significant for PNF cells." (PMID 31730023, 2019). "The further molecular analysis verified the cells expressing NF1 variant p.(Gln181Profs∗20) partially enhanced Ras activity and elevated cell proliferation and tumor formation due to loss of neurofibromin function caused by the variant." (PMID 31886188, 2019). "We subsequently sequenced the primary tumor, which harbored the same homozygous NF1 variant (VAF 82%)." (PMID 31443247, 2019). "Lastly, the findings advocate that tumor stratification by co‐mutations to KRAS/NF1 highlights the LAUD patient population expected to be susceptible to inhibiting PSAT1." (PMID 31036704, 2019). "Loss of Nf1 activates RUNX1/3 to enable tumor initiation by repressing Pmp22 through alternative promoter usage and other mechanisms to induce protein level expression of PMP22." (PMID 31032403, 2019). "GRM3 and NF1 were mutated at 38% and 21%, respectively, with mutations distributed along the gene coding regions, consistent with their tumor suppressor nature." (PMID 30312528, 2019).
tumor (continued). "Genetic analysis of tumor samples only identified a significant number of inactivating mutations in the RASGAPs neurofibromin (NF1) and RASA1 (p120GAP), suggesting that these two RASGAPs can function as tumor suppressors." (PMID 30858928, 2019). "Second, most NF1-associated neoplasms are of the benign type and rarely, if ever, progress to malignant tumors." (PMID 30479396, 2018). "NF1 (Neurofibromin 1) acts as a tumor suppressor by turning off KRAS and its mutation is often mutually exclusive with KRAS, as it imposes a functional activation of the RAS pathway." (PMID 30338041, 2018). "The results of our wide-genome study indicated a 10-fold increase of NF1 gene expression encoding for neurofibromin protein which act as a tumor suppressor that prevent cells from growing and dividing too rapidly or in an uncontrolled way." (PMID 29966337, 2018). "Molecular genetic analysis also revealed unique genomic alterations in the transformed tumor cells, including gain of NF1 and loss of TRAF3." (PMID 29463311, 2018). "Unsupervised clustering of genes from this WGCNA module with METABRIC clinical data revealed a strong association of NF1 shallow deletions in both ER+ and ER- tumor subsets." (PMID 30182054, 2018). "NF-1 is a tumor suppressor gene encoding a neurofibromin, namely GTPase-activating protein that negatively regulates p21-RAS signaling." (PMID 30445769, 2018). "The minipig provides a human-sized platform for imaging studies to better evaluate tumor natural history and therapeutic efficacy and to develop methods for early detection of NF1-associated tumors." (PMID 30302402, 2018). "It includes oncogenes—rearranged during transfection (RET) proto-oncogene and H-ras GTPase proto-oncogene (HRAS)—and several tumor suppressors: neurofibromin 1 (NF1), transmembrane protein 127 (TMEM127), and MYC-associated factor X (MAX)." (PMID 30345003, 2018). "Our results suggested that tranilast inhibits EMT-like changes and angiogenesis-related gene expression and shows potential antitumour activity for NF1-mutated tumour cells." (PMID 29666462, 2018). "Many evidences have suggested NF1 as a tumor suppressor gene as inactivation of both NF1 alleles would reduce the control of cell proliferation and lead to tumorigenesis." (PMID 30290804, 2018). "LB affected the cellular proliferation by increasing 10 times (Fc) the NF1 gene encoding for the neurofibromin protein, a tumor suppressor that prevent cells from uncontrolled proliferation." (PMID 29966337, 2018). "The cNF models should initiate from a small group of cells of origin that harbor NF1 loss, and the tumor histology and pathology should be similar to human cNF." (PMID 29987131, 2018). "And, NF1 is caused by loss-of-function mutations in NF1, which encodes neurofibromin, a protein that functions as a tumor suppressor through repressing the RAS pathway." (PMID 29590641, 2018). "Using two independent mouse models, we observed a faster appearance of benign tumors in the context of NF1- and non-NF1- associated tumors." (PMID 30479396, 2018). "The most common tumor in adults with NF1 is cNF, presumably resulting from the biallelic loss of NF1 in the Schwann cell lineage." (PMID 29987131, 2018). "Multiple studies reported MPNST associated with NF1 to present at younger age of onset (mean age of 26 years compared with 35 years in the general population), greater tumour size and higher disease stage." (PMID 30187267, 2018). "Neurofibromin 1 (NF1) is a tumor suppressor gene encoding a Ras GTPase that negatively regulates Ras signaling pathways." (PMID 29354122, 2017). "Since NF1 deficient tumor cells are generally characterized by over-activation of Ras and, as we demonstrated, by CRABP2 expression, the combination of MEKi and ATRA seems to be a promising new approach, necessarily to be validated in animal experiments." (PMID 29131833, 2017).
tumor (continued). "This patient’s case illustrates the considerable heterogeneity observed in NF1-associated tumors, even within areas of the same tumor." (PMID 29137242, 2017). "Further, it is anticipated that with the advent of powerful sequencing technologies, combined with precise microdissection of tissue, somatic NF1 mutations will be identified in additional tumour types." (PMID 28637487, 2017). "We performed a statistical analysis to assess possible associations of clinical parameters such as gender, location of the primary tumor and sample type (primary, metastasis or recurrence) with the NF1, RAS and RAF mutational status." (PMID 28380455, 2017). "In our cohort of 100 patients with NF1, we have shown that tumours in the thalamus are more likely to be associated with radiological progression, high-grade tumours, and surgical intervention." (PMID 28593402, 2017). "NF1 is a tumour suppressor gene, where loss of function mutations are associated in humans with the autosomal dominant syndrome Neurofibromatosis type 1." (PMID 28821767, 2017). "The NF1 gene, one of the largest genes in humans (60 exons), encodes neurofibromin, which is a tumour suppressor that downregulates the RAS–RAF–MAPK signalling cascade." (PMID 28471419, 2017). "GATK-based analysis of OV10 also detected a large insertion in PIK3CA, a missense variant in ARID1A (p.Ala532Thr) observed in only 2/25 tumor and 0/100 normal reads, and an NF1 large insertion that introduces a stopgain." (PMID 28852190, 2017). "Previously, our lab developed a high throughput approach using yeast and mammalian screening platforms to identify tool compounds and drug targets for cancer cells in which NF1 loss drives tumor formation." (PMID 28166733, 2017). "The NF1 gene encodes a tumor suppressor called neurofibromin 1, which through its GTPase-activating protein (GAP) domain negatively regulates Ras signaling keeping cell proliferation in check." (PMID 28813519, 2017). "We have shown that tumours in the thalamus are more likely to be associated with high-grade tumours in NF1." (PMID 28593402, 2017). "Somatic NF1 mutations are present in tumours associated with NF1 and in a range of sporadic tumours, in different cell types and at various frequencies." (PMID 28637487, 2017). "A machine learning classifier for transcriptomic data was able to detect signal associated with the inactivation of NF1, a tumor suppressor gene." (PMID 28166733, 2017). "Exome sequencing of Tet2−/− tumours reveals accumulation of numerous mutations, including Apc, Nf1, Flt3, Cbl, Notch1 and Mll2, which are recurrently deleted/mutated in human haematological malignancies." (PMID 28440315, 2017). "The MIR365B gene, locatedwithin the NF1 microdeletion region, also encodes an miRNA withknown tumour suppressor function, as evidenced by its ability to target specifictranscription factors, such as NKX2-1 and TTF1, in non-small cell lung cancer." (PMID 28213670, 2017). "We selected two MPNST cell lines, one a spontaneous non-NF1-associated tumor and the other an NF1-associated tumor-derived cell line, to perform flow cytometric analysis of immunologic molecule expression." (PMID 29137242, 2017). "Germline loss of function mutations in neurofibromin, a RAS-GAP that acts as a negative regulator of RAS signaling, are linked to neurofibromatosis type 1 (NF1), and predispose NF1 individuals to development of a variety of tumor types including GIST." (PMID 28768491, 2017).